FASN (fatty acid synthase)
Diseases named in the same sentence as FASN in open-access papers (continued):
Sharing a sentence is not in itself a finding about the gene and the disease.
kidney disease (2 papers, 2008 to 2023). "Furthermore, our work identifies ACSS2 and FASN as potential pharmacological targets for kidney disease." (PMID 38051585, 2023). "Genetic deletion of FASN protects against kidney disease development." (PMID 38051585, 2023). "We tested the role of FASN in adenine-induced kidney disease and the UUO models." (PMID 38051585, 2023). "Protein levels of SCAP, FASN, PLIN2, NLRP3, and GSDMD were higher in fibrotic human kidney tissue samples, likely indicating that DNL could be associated with kidney disease." (PMID 38051585, 2023). "Additionally, we discovered that pharmacological inhibition or genetic ablation of fatty acid synthase safeguarded kidney cells against profibrotic gene expression and prevented kidney disease in mice." (PMID 38051585, 2023). "Two notable predictions in this region are TSC2, which is already known to be related to kidney disease, and FASN, which may be involved in apoptosis." (PMID 18564415, 2008). "We show that small molecules, such as FASNall, which targets FASN, and ACSS2i, which targets ACSS2, protected mice from developing kidney disease." (PMID 38051585, 2023). "Deletion of SCAP or FASN in tubule cells or pharmacological inhibition of FASN protected cultured tubular cells from profibrotic gene expression and mice from tissue fibrosis, highlighting the importance of DNL in kidney disease development." (PMID 38051585, 2023). "Healthy controls and kidney disease samples showed strong expression of DNL genes, including ACSS2, NR1H3 (liver X receptor α [LXRA]), NR1H4 (farnesoid X receptor [FXR]), SREBF1, SCAP, PLIN2, PLIN5, ACACAB, ATP citrate lyase (ACLY), and FASN in PT cells and some other tubule cells." (PMID 38051585, 2023).
myopathy (1 paper, 2024). A disease of the muscle in which the muscle fibers do not function properly. "We selected four up-regulated genes for general myopathy (MGST1, AOX1, FASN, PRKCD), CD163 for IBM, and CYP4B1 for titinopathy, aiming to validate their actual expression in our local muscles." (PMID 38600180, 2024). "The genes featured for general myopathy indeed showed relatively higher expression trend in the myopathy muscles: MGST1 (RQ 10.34/2.09, p = 0.02), AOX1 (RQ 4.53/2.41, p = 0.42), FASN (RQ 3.75/1.75, p = 0.10), PRKCD (RQ 2.10/1.23, p = 0.19)." (PMID 38600180, 2024). "The top five up-regulated genes in general myopathy are MGST1, AOX1, FASN, PRKCD, and CHRNA1, which have been rarely reported in previous myopathy studies." (PMID 38600180, 2024).
FASN also shares sentences with these, for which no sentence is quoted: cardiovascular disease (8 papers); tuberculosis (8); meningioma (4); bladder tumor (3); breast (3); chronic lymphocytic leukemia (3); dyslipidaemia (3); gastric adenocarcinoma (3); overnutrition (3); T-cell leukemia (3); Barrett esophagus (2); Cirrhosis (2); gastric-tumor (2); head and neck squamous cell carcinoma (2); infectious disease (2); injury (2); metastatic colorectal cancer (2); pancreatic adenocarcinoma (2); pancreatic neuroendocrine neoplasm (2); salivary duct carcinoma (2); Age-Related Hearing Impairment (1); allergic asthma (1); anemia (1); aortic aneurysm (1); arteriosclerosis (1); atopic dermatitis (1); Autoimmunity (1); bacterial infections (1); benign cystadenomas (1); benign tumors (1).
A further 70 diseases each share a sentence with FASN in 1 paper.